KRT8 (keratin 8)
Diseases named in the same sentence as KRT8 in open-access papers (continued):
Sharing a sentence is not in itself a finding about the gene and the disease.
tumor (361 papers, 2005 to 2026). "Aberrant KRT8 expression has been linked to enhanced tumor plasticity, epithelial-mesenchymal transition (EMT), and increased metastatic potential." (PMID 41203621, 2025). "Aberrantly high expression of KRT8 has been found to be associated with multiple tumor progressions including cell migration." (PMID 35664775, 2022). "We found one intergenic SNV of KRT8 (Keratin 8) whose upregulation is linked to rapid tumor progression in multiple cancers, including gastric, lung, renal, and breast, and has been proposed as a pan-cancer early biomarker." (PMID 36011407, 2022). "Aberrant expression of KRT8 is associated with multiple tumor progression and metastasis; so is CUX1." (PMID 35428183, 2022). "KRT19, an intermediate filament protein, contributes to cytoskeletal organization and epithelial integrity in luminal subtypes (e.g., MCF7 and T47D) and is associated with cell adhesion and tumor progression via interactions with KRT8, KRT18, and EPCAM, as suggested by STRING analysis." (PMID 40806403, 2025). "Moreover, KRT8 has been indicated epithelial to mesenchymal transition, and loss of K8 phosphorylation was also suggested to promote tumor migration and formation of metastasis." (PMID 34876190, 2021). "Higher levels of KRT8 also significantly associate with tumor progression in NSCLC." (PMID 33777753, 2021). "Taken alone the reduction in keratin 8 expression associated with butyrate would be seen as a risk factor for tumour progression, although data would need to be interpreted against a wider panel protein alterations to establish whether the global risk was actually altered." (PMID 21219647, 2011). "Specifically, NAT10 enhances the stability of ETS2 and KRT8 mRNA via ac4C modification, thereby promoting tumor malignancy and immunosuppression." (PMID 41203621, 2025). "We found that the EDEM3 expression in epithelial cells (marked by KRT18, EPCAM, KRT8) was significantly higher in tumour tissues with a large proportion of CAFs (marked by COL1A1, COL1A2, COL6A1, COL6A2) in the GSE188711 CRC dataset." (PMID 39754316, 2025). "Targeting the NAT10-ETS2-PD-L1 axis while reducing KRT8-mediated tumor plasticity offers a novel approach for overcoming immune resistance and improving patient outcomes." (PMID 41203621, 2025). "In the CD45− population, clusters 0 and 1 were identified as major tumor clusters exhibiting high expression levels of epithelial cell markers (Krt8, Krt18, Krt19)." (PMID 40568084, 2025). "Expression of Keratin 8 was evaluated in all three cell lines as a marker for dysplastic and tumor cells." (PMID 40394426, 2025). "Therapeutic response was assessed by quantifying the number of cleaved caspase-3-positive cells among KRT8-positive tumor cells, which allows the evaluation of drug-induced tumor cell apoptosis." (PMID 40163511, 2025). "NAT10-mediated ac4C acetylation of KRT8 mRNA stabilizes its expression, contributing to tumor growth, migration, and invasion." (PMID 41203621, 2025). "In conclusion, this study established NAT10 as a central regulator of PC progression and immune evasion through the ac4C-dependent stabilization of ETS2 and KRT8 mRNA, thereby promoting tumor immunosuppression and malignancy." (PMID 41203621, 2025). "Progression from the first stage of tumor development to the metastatic stage is characterized by a decrease in cells expressing cytokeratin 8 (CK8), cytokeratin 18 (CK18), and the tumor suppressor gene p63." (PMID 40429906, 2025). "Single-cell analysis of KRT8 revealed that KRT8 was predominantly highly expressed in tumor epithelial cells." (PMID 41203621, 2025). "We observed distinct NE tumor cell clusters from snRNA-seq with variable KRT8 expression, consistent with the heterogeneity observed in NEPC by mIF." (PMID 39394434, 2024).
tumor (continued). "To further confirm that KACs give rise to tumour cells, we labelled KRT8+ cells in Gprc5a−/−;Krt8-creER;RosatdT/+ mice." (PMID 38418883, 2024). "Last, lineage-labelling of AT2 cells or KRT8+ cells following carcinogen exposure showed that KACs are possible intermediates in AT2-to-tumour cell transformation." (PMID 38418883, 2024). "Tumour epithelial cells were identified based on the expression of mCherry and the epithelial marker Krt8, whereas stromal cells were annotated using known cell type-specific markers." (PMID 38926506, 2024). "Consistent with their well-differentiated glandular morphology, RPM-Ascl1KO tumors were dominated by AR+;KRT8+ tumor cells." (PMID 39394434, 2024). "Analyses of omental tumor sections by mIF imaging revealed that clusters of Krt8+ tumor cells were closely adjacent to the tumor vasculature in untreated mice." (PMID 39372930, 2024). "EPCAM and KRT8 were abundantly expressed in tumor epithelial tissue with scattered expression of CD14 and CD163 in monocytes/macrophages." (PMID 38611120, 2024). "Remarkably, compared to control tumours which were KRT8 and pAMPK positive, GPx2 KD tumours contained KRT8/KRT14 positive areas that expressed pAMPK (in the cytosol) and GLUT1 (at the membrane) in same cells." (PMID 38238426, 2024). "Histologically, tumors from both intact and castrated mice exhibited KRT8+NKX3.1+ luminal-like regions along with SYP+INSM1+ NE tumor foci." (PMID 39024561, 2024). "Of note, most tumours showed tdT+KRT8+ cells at varying levels, with some tumours showing a strong extent of tdT labelling, which suggested oncogenesis of KRT8+ cells." (PMID 38418883, 2024). "Differences were also observed in colocalization of tumor vasculature and Krt8+ cells relative to collagen 1 1 (Col1 1) protein fibers that are known for adverse effect on T cell trafficking." (PMID 39372930, 2024). "To substantiate this classification, we examined the expression of hallmark canonical cell markers of cancer epithelial cells (EPCAM, SOX4, KRT7, KRT18, KRT19, KRT8) in C1 (normal epithelial cells) and the other clusters (tumour epithelial cells)." (PMID 38445456, 2024). "Quantification of GPx2 KD tumours and paired lung mets confirmed a higher percentage of carcinoma cells co-expressing p63 with KRT8/KRT14 than with KRT8 or KRT4 at both sites." (PMID 38238426, 2024). "Western blot results showed that after treatment with EZMLD, the expression level of KRT8 protein in tumor tissues of nude mice decreased significantly." (PMID 39103890, 2024). "High-resolution, multiplex imaging analysis of KRT8, CLDN4 and pan-cytokeratin (PanCK) showed that KACs were enriched in tumour-adjacent normal regions (TANs) and were found immediately next to malignant cells showing high expression of KRT8 and CLDN4." (PMID 38418883, 2024). "ST analysis of tumour tissue from patient P14 demonstrated increased expression of KRT8 in tumour regions (with high CNV scores) and in TAN regions that histologically comprised highly reactive pneumocytes and exhibited moderate-to-low CNV scores." (PMID 38418883, 2024). "By 10 weeks, larger homogeneous clusters of ASCL1+;KRT8− tumor cells with NEPC histology were visible." (PMID 39394434, 2024). "ST analysis at 7 months after NNK treatment showed that tumour regions had significantly increased expression of Krt8 and Plaur and had spatially overlapping KAC and KRAS signatures." (PMID 38418883, 2024). "A high/preferential expression of PTX3 occurs in the tumor cell subpopulations (CC_TNBC) characterized by the expression of Keratin 8 (KRT8) and high genomic instability." (PMID 37749607, 2023). "In line with the Krt6a upregulation, the basal marker Trp63 was also upregulated, while the expression levels of the luminal keratins Krt8/18 were lower in the KO tumours." (PMID 36933062, 2023). "Consistently, the cytokeratin tumor markers, KRT8, KRT18, and KRT19, were most abundantly expressed in these epithelial cells." (PMID 37430270, 2023).
tumor (continued). "The high purity of the fibroblast and tumor cell populations was confirmed by selective expression of cell type-specific genes including CDH1, EPCAM, and KRT8 for tumor cells and VIM, DCN, THY1, and COL3A1 for fibroblasts." (PMID 36868311, 2023). "Clusters 2, 6, and 11 expressed Keratin genes (Krt7, Krt8, and Krt18), suggesting their potential tumor origin." (PMID 37055410, 2023). "In order to trace the lineage of the MMTV-PyMT tumor cells, either Krt8 (luminal) or Krt5 (basal) specific, tamoxifen-inducible CreERT promoters were used to induce expression of GFP in an mTmG reporter mouse to label luminal or basal cells, respectively." (PMID 36859337, 2023). "Along these lines, most of the Krt5-expressing tumor cells also co-expressed Krt8, with only a small percentage of cells exclusively expressing the basal marker." (PMID 36859337, 2023). "Luminal-like tumor cells were identified by Krt8 expression, whereas basal-like tumor cells were identified by either Krt5 or Krt14 expression." (PMID 36859337, 2023). "Specifically, as tumor cells highly express epithelial features, typical epithelial markers including KRT8 and EPCAM are highly expressed in 6 clusters (0, 3, 6, 9, and 10)." (PMID 37479733, 2023). "KRT8 is regarded as an epithelial marker in tumour pathology partly because it is highly expressed in epithelial structures." (PMID 35958278, 2022). "For example, tumor cells showed particularly high expressions of KRT8, KRT18 and TCF7L1, whereas endothelial cells showed particularly high expressions of PECAM1 and VWF.." (PMID 35494058, 2022). "The results showed that KRT8 knockdown efficiently inhibited the growth of tumors measured by tumor size and number." (PMID 35664775, 2022). "The loss of DNA methylation is a common epigenetic alteration in human tumours and is widely described as a ubiquitous feature of carcinogenesis (reviewed in detail by Ehrlich 2009), thus supporting the role of KRT8 in cancer progression." (PMID 35204653, 2022). "KRT8 and KRT18 were highly expressed in Mel106, and they were extensively used as diagnostic tumor markers." (PMID 35646893, 2022). "For example, although tumor cells subtypes (such as tu_1, tu_2, tu_3, tu_5, tu_6, tu_8, and tu_9) have median normalized Keratin 8/18 expression around zero, they exhibit significantly higher Keratin 8_18 expression levels than non-tumor cells." (PMID 33917869, 2021). "KRT8 was highly expressed in LN+ BC and in patients dead from BC as it seemed to increase with the size and stage of the tumor." (PMID 31781306, 2019). "When measuring the relative tumor fractions of these populations, it was observed that Wnt1-LateEx tumors contained a higher fraction of Krt5-positive cells (P=0.02) and Krt8/18-positive cells (P=0.001) than Wnt1-EarlyEx tumors." (PMID 31213486, 2019). "Based on the results of these studies, KRT8 protein expression was measured in clinical ATC tumor specimens as well as in patient-derived xenograft (PDX) ATC cell lines." (PMID 29443941, 2018). "Among ATC patient tumor samples, there was heterogeneous KRT8 expression, ranging from low (nuance score 29) to highly elevated." (PMID 29443941, 2018). "There was the expected corresponding decrease in basal cell markers (KRT5 and TP63) and increase in expression of luminal cytokeratin markers in tumor cells (KRT8 and KRT18)." (PMID 27935821, 2017). "The staining density of the KRT8 protein in the tumor group was stronger than that in the peritumor group (average KRT8 protein density: 0.0072±0.00031 vs 0.0042±0.00017; P<0.0001; paired t test)." (PMID 29100303, 2017). "The tumor cells stillexpressed ERα but there was lower keratin 8/18 and higher keratin 14 staining asthe cells migrated from the ducts into the stroma." (PMID 25527189, 2014). "Immunofluorescence of PE tumor cells derived either directly from the patient or after culturing for 96 hours demonstrated the presence of both luminal (keratin-8 positive) and basal (keratin-14 positive) cell types." (PMID 23879992, 2013).
tumor (continued). "However, in tumor tissue, TGM1 and KRT8 levels showed a statistically significant association with T status." (PMID 41695373, 2026). "Tumor tissue samples were analyzed for KRT8 expression using immunohistochemistry." (PMID 40777008, 2025). "Furthermore, compared to tumor epithelial cells with low KRT8 expression, those with high KRT8 expression exhibited stronger interactions with T cells." (PMID 41203621, 2025). "KRT8, as a tumor tissue biomarker, may capture unique aspects of epithelial biology and immune susceptibility not reflected in circulating markers or radiographic changes." (PMID 40777008, 2025). "A notable example is the discovery of KRT8+ alveolar intermediate cells (KACs), located closer to tumor regions compared with alveolar cells, which represent an intermediate state in the transformation of alveolar type II (AT2) cells into tumor cells during early-stage lung adenocarcinoma (LUAD)." (PMID 41194170, 2025). "Third hypothesis: changes in KRT8 expression may potentially influence the tumor microenvironment, possibly affecting the recruitment and activation of immune cells." (PMID 40777008, 2025). "To examine whether phenotypic and metabolic plasticity were interrelated, we co-stained tumours for luminal (KRT8; yellow) and basal (KRT14; red) markers, along with OXPHOS (pAMPK; green) and glycolysis (GLUT1; blue) markers." (PMID 38238426, 2024). "Indeed, echinomycin-treated GPx2 KD tumours showed dramatic reductions in p63 and KRT14 levels, resulting in KRT8-enriched tumours, indicative of luminal differentiation." (PMID 38238426, 2024). "We triple co-immunostained tumours for p63, KRT8 (luminal) and KRT14 (basal) markers." (PMID 38238426, 2024). "Furthermore, fragments of keratin 8 released by lung cancer cells were utilized as an indicator of tumor progression in clinical studies." (PMID 39739089, 2024). "Indeed, PyMT2/gRNA2 tumours were luminal-like (KRT8+ or E-CAD+), as compared to control tumours which were E/M-like as shown by KRT8/KRT14 or E-CAD/VIM expression." (PMID 38238426, 2024). "Malign_2 expressed a number of markers associated with the fibroblast lineage suggesting that this tumor subtype has undergone epithelial mesenchymal transition (EMT), whereas, Malign_3 expressed elevated levels of Krt8 and 18 consistent with epithelial differentiation." (PMID 38802355, 2024). "DLL3 expression was limited to NE tumor foci and was mutually exclusive of KRT8 expression." (PMID 39024561, 2024). "Interestingly, these tumours harboured significantly less KRT8/KRT14 or E-CAD/VIM positive areas than vehicle-treated GPx2KD tumours, due to mesenchymal gene repression." (PMID 38238426, 2024). "Knockdown of KRT8 appreciably attenuated tumor growth in the mice." (PMID 38356715, 2024). "Interestingly, PyMT2 tumours were enriched in KRT8/KRT14 or E-CAD/VIM hybrid areas as compared to GPx2 OE tumours which expressed either KRT8 or E-CAD, indicative of mesenchymal to epithelial transition (MET)." (PMID 38238426, 2024). "Interestingly, GPx2 KD tumours also harboured areas that were either KRT14 or KRT8 positive (Area 2)." (PMID 38238426, 2024). "It is thus possible, and likely, that the luminal-derived basal-like tumor cells in the Krt8-CreERT/Rosa26-mTmG/MMTV-PyMT mouse may have descended from a luminal progenitor ancestor instead of a differentiated luminal cell." (PMID 36859337, 2023). "In order to allow the lung metastases to continue to grow beyond this point, we surgically resected the primary tumor from a Krt8-CreERT/Rosa26-mTmG/MMTV-PyMT mouse, and allowed the lung metastases to develop until the surgically resected tumor began to regrow." (PMID 36859337, 2023). "To investigate whether one lineage is important for metastasis than the other, we analyzed lungs from Krt5-CreERT/Rosa26-mTmG/MMTV-PyMT and Krt8-CreERT/Rosa26-mTmG/MMTV-PyMT tumor bearing mice." (PMID 36859337, 2023).
tumor (continued). "Surprisingly, stem cell markers and associated WNT signaling genes, including Lgr5, decreased in tumor cells along the treatment timeline in a gradient-like manner; this corresponded with increase in differentiated epithelial genes Krt20 and Krt8." (PMID 35600339, 2022). "Interestingly, most of these genes have been implicated in general mechanisms of tumor biology, such as SERPINF1, reported as an inhibitor of angiogenesis and tumor suppressor, ASAP2, an EGFR pathway activator, or ELN and KRT8 related to the process of EMT." (PMID 34758873, 2021). "In breast cancer keratin 8 negatively regulated TRAIL-induced apoptosis via DR5 which could be a marker as predictor of tumor resistance." (PMID 33171868, 2020). "While previous reports have suggested that KRT8 may play a role in either promoting or inhibiting the aggressive behavior of some cancers, this is the first report providing evidence that KRT8 is an important driver of ATC tumor cell survival." (PMID 29443941, 2018). "We found that KRT8 expression was upregulated in ccRCC and vein tumor thrombi (VTTs)." (PMID 29100303, 2017). "We therefore further examined KRT8 expression during late stages of tumor development in our model." (PMID 27344183, 2016). "Moreover, tumors from TGFBR1-CACcre ovaries were highly proliferative, expressed granulosa cell markers FOXL2 and INHA, and were immunoreactive for KRT8 during tumor progression." (PMID 27344183, 2016). "Lineage tracing studies using CreERT2 recombinase expressed from KRT8 + luminal progenitor and mature cells confirmed their clonal expansion in both lineages upon oncogenic PI3K signaling and revealed that reactivation of multipotency causes a mixed-lineage tumor phenotype." (PMID 40676433, 2025). "Importantly, IL-11 mRNA levels were correlated with KRT8 transcript levels in tumor tissues." (PMID 29100303, 2017). "We used keratin expression (KRT7, KRT8, and KRT19) to visualize the tumor area and CD68 to mark myeloid cells." (PMID 40917508, 2025). "Functional experiments further confirmed that KRT8 and PERP promote tumor proliferation and migration, providing new insights into their roles as therapeutic targets." (PMID 39895784, 2025). "Similar to neoplasms of the same histopathologic subtypes in humans, all TSG101-induced mammary tumors were comprised of cytokeratin 8 and 18 (CK8/18)-positive luminal epithelial cells and basal cells expressing CK5 and CK14 (upper)." (PMID 40624726, 2025). "Focused on this cluster number “3”, cells from the three samples were found to express some epithelial/tumor markers at distinct levels, with markers including EPCAM, CD44, KRT8, ITGA6, and CLDN4." (PMID 41440935, 2025). "In our analysis, both KRT8 and S100A16 were upregulated in LUAD tumor tissues, reinforcing their roles in LUAD progression and highlighting their potential as immune-related therapeutic targets." (PMID 41239716, 2025). "The EMT marker proteins, such as VIM, KRT18, KRT8, and MMP9 are involved in cell structure, motility, and matrix remodeling, which are crucial for tumor invasion and metastasis." (PMID 39858010, 2025). "Integrating our findings, we observed that knocking down KRT8 in A549 and PC9 cell lines resulted in the suppression of tumor cell proliferation and invasion." (PMID 39895784, 2025). "Malignant epithelial cells expressed secretory markers including EPCAM, cytokeratins (KRT8/10/18), MUC16, the carrier of the CA125 tumor marker, and mesothelin (MSLN), an OC differentiation antigen." (PMID 40164596, 2025). "By 8–10 weeks, primary and metastatic tumor cells were mostly AR− and ASCL1+ with heterogenous KRT8 and E-cadherin expression." (PMID 39394434, 2024). "The peaks of epithelial cells and tumor cells were notably enriched in the gene sets of ‘VIM, KRT5, KRT17’ and ‘KRT8, KRT18, FOXA1’, respectively." (PMID 38581422, 2024).